NOTCH3 (notch receptor 3)
Diseases named in the same sentence as NOTCH3 in open-access papers (continued):
Sharing a sentence is not in itself a finding about the gene and the disease.
colon carcinoma (21 papers, 2013 to 2024). "We show that our approach outperforms existing methods and that the top genes identified by our process are implicated in NOTCH3 signaling and general metabolism pathways, which are essential to colon cancer progression." (PMID 36672162, 2023). "In summary, these findings suggest that elevated NOTCH3 expression correlates with poor survival outcomes in colon cancer and is associated with altered immune cell infiltration and immune checkpoint expression, highlighting its potential as a prognostic marker and therapeutic target." (PMID 39130639, 2024). "Depletion of APJ or Notch3 abolished APL13 or JAG1-associated proliferation of colon carcinoma." (PMID 29254197, 2017). "FGA and NOTCH3 play significant roles in exercise-induced muscle adaptation and colon cancer progression." (PMID 39130639, 2024). "Analysis of NOTCH3-4 expression profiles in colon cancer identified high expression of NOTCH3 as significantly associated with poor prognosis." (PMID 39130639, 2024). "Immunohistochemical staining demonstrated a notable increase in NOTCH3 expression in colon cancer tissues compared to normal tissues." (PMID 39130639, 2024). "Using bioinformatics analysis and clinical sample validation, we found that Notch3 was highly expressed in colon tumor tissues compared to adjacent normal tissues, and it participated in regulating the recruitment of macrophages to the tumor microenvironment." (PMID 36647017, 2023). "Then, the expression levels of Notch receptors in colon cancer tumors and normal tissues were analyzed, and we showed that only the level of Notch3 was highly expressed in tumor tissues." (PMID 36647017, 2023). "Altogether, our results suggested that Notch3 participated in regulating the recruitment of macrophage in colon cancer, thereby regulating tumor progression." (PMID 36647017, 2023). "The levels of APJ and Notch 3 protein and mRNA levels were significantly increased in colon carcinoma in contrast to those in the adjacent normal tissues." (PMID 29254197, 2017). "For example, the overexpression of NOTCH3 could enhance the growth of colon cancer cells HCT 116 and SW 480, whereas the combination of AS-IV and cisplatin dramatically enhances the susceptibility of colon cancer cells to cisplatin." (PMID 39064966, 2024). "Furthermore, we found that the Notch3 expression was positively correlated with the expression of macrophage recruitment-related cytokines in colon tumor tissues." (PMID 36647017, 2023). "In contrast, Notch3 has been shown to be highly expressed in colon cancer." (PMID 29104587, 2017). "It remains to be investigated whether the expression levels or functions of factors involved in miR-1-mediated downregulation of NOTCH3 are altered in colon tumors." (PMID 24244701, 2013). "The involvement of NOTCH3 and SMARCA4 in the regulation of colon cancer was proved via direct interaction with endogenous and exogenous co‐IP and GST‐pulldown experiments." (PMID 35900231, 2022). "Exogenous apelin had anti-apoptotic effects on colon cancer cells, whereas in human colon cancer cell lines, this peptide stimulated proliferation through the JAG-1/Notch3 signalling pathway." (PMID 30127323, 2018). "mRNA expression levels of NOTCH-1, NOTCH-3, NOTCH-4, JAG-1, DLL-4, Hes-1, and Hey-1 were quantified to elucidate the action of endostatin/CTX on the notch signaling pathway in colon cancer." (PMID 26762567, 2016). "The protein expression patterns of NOTCH3 and SMARCA4 may be closely related to the prognosis of patients with colon cancer." (PMID 35900231, 2022). "DFS-induced FoxM1 degradation was blocked by treatment with chloroquine in colon cancer cells, while the levels of Notch 3 and E-cadherin were not changed by DFS." (PMID 28378765, 2017).
colon carcinoma (continued). "In addition, Notch3 was highly expressed in colon cancer tissues compared to normal tissues." (PMID 36647017, 2023). "In addition, the possible targeting factors of NOTCH3 and SMARCA4 in colon cancer cells were screened through RNA‐seq, and, for the first time, we identified that MUC5AC and MUC2 may be the targeted factors for the co‐regulation of NOTCH3 and SMARCA4 interaction." (PMID 35900231, 2022). "Interestingly, apelin peptides did not increase the proliferation of the colon cancer cells, whereas it did stimulate the phosphorylation of Akt kinase, whereas in human colon cancer cell line LS180, administration of apelin-13 stimulated proliferation via the JAG-1/Notch3 signaling pathway." (PMID 29875677, 2018).
ischemic stroke (21 papers, 2012 to 2025). A stroke disorder caused by obstruction of blood flow to the brain, due to thrombotic (local blood clot formation) or embolic (due to a blood clot or other material traveling from another site) event. "detected one pathogenic NOTCH3 variant in their cohort of 22 juvenile stroke patients ≤ 56 years with familial clustering of ischemic stroke corresponding to a frequency of 4.5%." (PMID 36411388, 2023). "Among these, 16 patients with NOTCH3 mutations had an average age at onset of 42.2 ± 13.8 years, with ischemic stroke or TIA being the most common clinical symptom (11, 68.8%)." (PMID 37237429, 2023). "Recently, homozygous nonsense NOTCH3 mutations were identified in two patients with Snedden syndrome, a very rare disease that causes ischaemic strokes." (PMID 35472289, 2022). "Here, we showed that 2 different human CADASIL mutations (Notch3 R90C or R169C) worsen ischemic stroke outcomes in transgenic mice; this was explained by the higher blood flow threshold to maintain tissue viability compared with that in wild type (WT) mice." (PMID 35202003, 2022). "This increase in risk is primarily via ischemic stroke for NOTCH3 and HTRA1 and via intracerebral hemorrhage for COL4A1/2." (PMID 36300346, 2022). "It is a major monogenic cause of ischemic stroke and it is related to a pathogenic variant of the NOTCH3 gene that is inherited in an autosomal-dominant way." (PMID 35741740, 2022). "NOTCH3 carriers had a threefold increased risk of ischaemic stroke (OR 3.07, 95% CI: 1.81 to 5.23, p<0.001), while a 1 SD increase in ischaemic stroke PRS increased the odds by 26% (OR: 1.26, 95% CI: 1.21 to 1.32, p<0.001)." (PMID 33712516, 2021). "Further analyses including overall subtypes of ischemic stroke are necessary to confirm the exact prevalence of NOTCH3 mutations in the future." (PMID 32477100, 2020). "Consistent with our finding, a previous study that assessed NOTCH3 variants revealed that only one of 39 variants was associated with an increased risk of ischemic stroke with small vessel disease subtype in Caucasians33." (PMID 30692550, 2019). "Another study showed that only some of the NOTCH3 variants were associated with ischemic stroke in Chinese patients." (PMID 30692550, 2019). "The strength of the association between NOTCH3 polymorphisms and ischemic stroke risk and its subtypes were measured as odds ratios and 95% confidence intervals, under different genetic models." (PMID 31288479, 2019). "In the combined Caucasian series, the only common NOTCH3 variant that was significantly associated with ischemic stroke after correction for multiple testing was p.R1560P (rs78501403, OR: 0.50, 95% CI: 0.31-0.79, P=0.0022)." (PMID 24086431, 2013). "Herein, we present a complete exon screening of NOTCH3 in 269 Caucasian probands with familial ischemic stroke and follow-up the identified variants in an association approach with a Caucasian and African-American patient-control series." (PMID 24086431, 2013). "We identified 39 variants in our comprehensive sequencing of the NOTCH3 gene in the 269 familial ischemic stroke probands and 95 control subjects." (PMID 24086431, 2013). "This is particularly true in the African American series and in examination of associations of NOTCH3 variants with ischemic stroke subtypes." (PMID 24086431, 2013). "Future studies that determine whether the NOTCH3 rs1044009 polymorphism affects ischemic stroke risk or lacunar stroke risk using a prospective cohort study design rather than using a case-control design is warranted." (PMID 31288479, 2019). "Given the reduced penetrance and clinical heterogeneity, we hypothesized that NOTCH3 variants may play a greater role in ischemic stroke than previously thought." (PMID 24086431, 2013). "Cysteine-affecting NOTCH3 mutations are rare in patients with typical ischemic stroke, however our observation that common NOTCH3 variants may be associated with risk of ischemic stroke warrants further study." (PMID 24086431, 2013).
ischemic stroke (continued). "In addition, we examined if other coding variants in NOTCH3, common or rare variation, affect the individual susceptibility to ischemic stroke." (PMID 24086431, 2013). "The association of NOTCH3 p.R1560P suggests that disruption of the normal NOTCH3 receptor function could modulate the risk of ischemic stroke." (PMID 24086431, 2013). "As a result, power to detect associations of NOTCH3 variants with ischemic stroke and ischemic stroke subtypes is low, and the possibility of Type II error (i.e. a false-negative association) is important to acknowledge, especially after correction for multiple testing." (PMID 24086431, 2013). "Hence, we carried out this meta-analysis to investigate whether NOTCH3 rs1043994, rs1044009 and rs3815188 polymorphisms are associated with ischemic stroke and its major subtypes." (PMID 31288479, 2019). "However, the role of NOTCH3 gene polymorphisms in the risk of ischemic stroke, and its subtypes such as atherothrombotic or lacunar strokes, remains unclear." (PMID 31288479, 2019). "For NOTCH3 and HTRA1, cardiovascular risk factors, as assessed by the FRS, increased ischemic stroke risk in variant carriers, and there was a statistical interaction between variant status and FRS." (PMID 36300346, 2022). "NOTCH3 and HTRA1 variant carriers were associated with the same ischemic stroke risk as belonging to the upper 0.1% and 0.2% of the population, respectively." (PMID 36300346, 2022). "This analysis was limited to NOTCH3 and HTRA1 because significant associations with ischemic stroke had only been found for these variants." (PMID 36300346, 2022). "However, whether or not cysteine-sparing mutations are correlated with ischemic stroke remains debatable, although excessive accumulation and deposition of NOTCH3 in the small resistance arteries may cause arteriopathy, and thus reduce cerebral blood flow during the development of ischemic stroke." (PMID 31288479, 2019). "All 33 exons of NOTCH3 were sequenced in 269 Caucasian probands from the Siblings With Ischemic Stroke Study (SWISS), a 70-center North American affected sibling pair study and 95 healthy Caucasian control subjects." (PMID 24086431, 2013). "Deficiency of Notch3 has been shown to disrupt VSMC differentiation and to increase infarct size in ischemic stroke." (PMID 22558265, 2012). "Lastly, a VUS in NOTCH3 (p.Gly1710Asp) was found in a patient with lacunar stroke, which has been reported in association with cerebral white matter lesions but not ischemic stroke." (PMID 36411388, 2023). "Among these mutations, NOTCH3 rs1043994, rs1044009 and rs3815188 have been associated with ischemic stroke in Chinese populations, but not Japanese and Caucasian populations." (PMID 31288479, 2019). "Despite these limitations, this is the most comprehensive meta-analysis that provides solid evidence for the non-significant association of NOTCH3 polymorphisms with ischemic stroke and its major subtypes (i.e., atherothrombotic and lacunar)." (PMID 31288479, 2019). "NOTCH3 signaling may exert a beneficial effect on the pathogenesis of ischemic stroke, by protecting against vascular smooth muscle cells apoptosis." (PMID 31288479, 2019). "The role of other exonic NOTCH3 variation not involving cysteine residues and mutations in exons 25-33 in ischemic stroke remains unresolved." (PMID 24086431, 2013). "It will also be interesting to further explore whether an earlier onset of the ischaemic strokes in the three NOTCH3 null patients identified thus far, as compared with CADASIL patients, is a consistent feature and may reflect more dramatic vascular aberrations." (PMID 35472289, 2022). "Moreover, their results were limited to the allelic models of NOTCH3 rs1043994 and rs3815188 polymorphisms, and no information was available on ischemic stroke subtypes." (PMID 31288479, 2019).
ischemic stroke (continued). "Univariate and multivariate analyses demonstrated that despite NOTCH3 rs3515188, rs1043994 and rs1044009 polymorphisms exerting susceptibility risks towards and/or protective risks against, ischemic stroke in both ethnicities, they were not statistically significant." (PMID 31288479, 2019). "However the actual pathomechanism behind NOTCH3 mutations that are characteristic of CADASIL and ischemic stroke remains unclear." (PMID 24086431, 2013). "We confirmed the presence of significant correlations of NOTCH3 p.R544C, FV-H1299R, MTHFR-C677T, MTHFR-A1298C, FII Prothrombin, FV-Cambridge, PAI1 4G/5G, and FXIII Val34Leu with several factors in patients with ischemic stroke." (PMID 38935968, 2024). "Hence, subgroup analysis stratified by populations was not undertaken for the association of NOTCH3 rs1043994, rs3815188 and rs1044009 polymorphisms with ischemic stroke and its subtypes, due to less than three studies reported in non-Asian populations in most of the genetic models." (PMID 31288479, 2019). "In contrast, genetic propensity to common ischemic stroke, as assessed by PRS, was only associated with increased risk in individuals without NOTCH3 or HTRA1 variants." (PMID 36300346, 2022). "The rates of ischemic stroke occurrence were not significantly different among the typical CADASIL, SVCI with NOTCH3 variants, and SVCI without NOTCH3 variants groups." (PMID 30692550, 2019).
melanoma (21 papers, 2016 to 2026). A malignant, usually aggressive tumor composed of atypical, neoplastic melanocytes. "In other studies, Notch3 was instead linked to tumor suppressive activity, e.g., its overexpression in breast and melanoma cell lines was found to increase p21 and thereby inhibit cell proliferation and induce cell senescence." (PMID 29462871, 2018). "In melanoma, Notch3 had been linked to invasion-migration properties of the cells." (PMID 35884426, 2022). "Furthermore, Notch3 silencing using lentiviral shRNA attenuated both tumor growth and VM in melanoma stem-like cells, suggesting that Notch3 is closely associated with tumor angiogenesis." (PMID 31772665, 2019). "This was further supported by mRNA analysis of a 442-patient melanoma data set obtained from TCGA, altogether supporting the importance of the Notch3/WNT5B axis in melanoma aggressiveness." (PMID 37971882, 2024). "This highlights the role of Notch3 in the capacity for initiating metastasis, even in a cohort with melanoma cases, which are less aggressive than the extremely aggressive cases in our cohort." (PMID 37971882, 2024). "Here we show that Notch3 is not only contributing to the more aggressive melanoma cell characteristics but can also elicit functions that modify the melanoma tumor microenvironment, and thereby promote cancer progression." (PMID 37971882, 2024). "To that end, we set up cocultures of LECs with WM852 and WM165 melanoma cells pretreated with control siRNAs (siCtrl*) or siRNAs targeting NOTCH3 24 hours prior to the start of the 48-hour coculture." (PMID 37971882, 2024). "We next investigated how Notch3 activation is induced in the melanoma cells upon interaction with LECs in coculture." (PMID 37971882, 2024). "To look for further evidence for the importance of Notch3 and WNT5B in the aggressiveness of melanoma, we performed Kaplan-Meier survival association analyses for both genes using the 442 patient cohort from TCGA." (PMID 37971882, 2024). "We have previously shown that Notch3 is highly upregulated in melanoma cells upon coculture with LECs and is important for melanoma invasion and metastasis." (PMID 37971882, 2024). "Our data also demonstrated that metastatic samples from a patient cohort with particularly aggressive melanoma showed a significantly higher correlation for Notch3 and WNT5B coexpression when compared with the primary tumors." (PMID 37971882, 2024). "We further found that Notch ligand DLL4, expressed in LECs, is a potent inducer among the tested ligands of Notch3 in melanoma cells." (PMID 37971882, 2024). "Our previous report demonstrated that the LEC-induced Notch3 is crucial for the increased melanoma invasion." (PMID 37971882, 2024). "A bi-directional DLL4/Notch3/WNT5B-dependent signaling cascade underlies crosstalk between melanoma and lymphatic endothelial cells and promotes melanoma lymphatic metastasis." (PMID 37971882, 2024). "Together, these data demonstrate that Notch3 acts as an upstream positive regulator of WNT5B in the metastatic melanoma cell lines WM852 and WM165." (PMID 37971882, 2024). "Notch3 is a central protein in changing melanoma cell behavior; its effects include induction of increased cell migration, stem-like cell characteristics, and invasion and metastasis." (PMID 37971882, 2024). "Specifically, we show that DLL4, expressed on the LEC surface, activates Notch3 in melanoma cells, which in turn triggers WNT5B transcription and protein expression in melanoma cells." (PMID 37971882, 2024). "This further supports our findings from the functional assays that the Notch3/WNT5B axis has an important role in melanoma aggressiveness." (PMID 37971882, 2024). "We and others have previously demonstrated that endothelial cells induce Notch3 expression in melanoma cells upon interaction." (PMID 37971882, 2024). "WNT5B upregulation was mediated by Notch3 activation induced in melanoma cells by direct interaction with LECs upon coculture." (PMID 37971882, 2024).